PVALB (parvalbumin)
Diseases named in the same sentence as PVALB in open-access papers (continued):
Sharing a sentence is not in itself a finding about the gene and the disease.
autism (44 papers, 2011 to 2026). Persistent deficits in social interaction and communication and interaction as well as a markedly restricted repertoire of activity and interest as well as repetitive patterns of behavior. "Single-nuclei RNA sequencing of the dorsolateral prefrontal cortex revealed an excitatory/inhibitory imbalance-specifically, reduced parvalbumin-positive interneurons and synaptic dysregulation-accompanied by downregulation of autism-risk genes." (PMID 42130747, 2026). "It has also been reported that parvalbumin-knockout (PV(−/−)) mice show developmental neuroanatomical changes associated with autism, including cortical hypertrophy and cerebellar hypoplasia." (PMID 40906373, 2025). "Alterations to parvalbumin (PV) expressing interneurons have been implicated in the neuropathological and behavioral deficits in autism." (PMID 36998537, 2023). "For example, deletion of the autism-risk gene contactin-associated protein 2 (Cntnap2) reduced the number of GABAergic interneurons in mouse cortex, including fast-spiking parvalbumin-immunopositive interneurons." (PMID 36768529, 2023). "We provide morphological evidence that accumulation of N-tr-Aβ, which previously has been linked to a local oxidative stress in idiopathic and dup-15 autism, mainly affects the parvalbumin-expressing subpopulation of GABAergic neurons." (PMID 32345355, 2020). "Across the germinal zones, autism genes associated with transcriptional regulation showed peak expression in neural progenitors in the medial ganglionic eminences, the primary origin of parvalbumin- and somatostatin-expressing interneurons." (PMID 41279531, 2025). "We show that mice expressing excessive β-cat display behavioral and molecular changes, including decreased social interest, increased repetitive behaviors, reduced parvalbumin and altered expression levels of additional genes identified as potential risk factors for human autism." (PMID 32296324, 2020). "In line with the role of parvalbumin neurons in normal brain circuitry and oscillations, this distinct association might underscore the excitation-to-inhibition ratio imbalance in autism." (PMID 35680911, 2022). "There is increasing evidence in the literature that parvalbumin-positive neuron dysfunction is directly related to the pathogenesis of autism." (PMID 40906373, 2025). "The number of chandelier (Ch) cells, an inhibitory interneuron subtype that expresses the calcium-sequestering protein parvalbumin (PV), is decreased in prefrontal cortex Brodmann Areas (BA) 9, 46, and 47 in autism." (PMID 37097993, 2023). "E2 increases GAD-67+ (also known as GAD1+) GABAergic interneurons in a rat model of IS and elevates parvalbumin expression in a Pvalb KO model of autism with rescue of aberrant phenotypes." (PMID 32033960, 2020). "Previous work in an autism-unrelated mouse strain demonstrated that GABAergic parvalbumin neurons in the primary motor cortex are essential for the inhibition of sensory-triggered motor reaction behaviors." (PMID 32508576, 2020). "We propose that deposition of N-tr-Aβ specifically affects the functions of the parvalbumin-expressing GABAergic neurons and results in a dysregulation of brain excitatory–inhibitory homeostasis in autism." (PMID 32345355, 2020). "Altogether our findings show that neurophysiological impairments of hearing perception in this autism model occur independently of alterations in the number of parvalbumin-expressing interneurons." (PMID 26635548, 2015). "Other types of interneurons may also be involved in the pathology of autism but have received less research attention because PVALB is among the most down-regulated genes in the autistic cerebral cortex." (PMID 40906373, 2025). "Interestingly, the number of parvalbumin-expressing interneurons is decreased in the prefrontal cortex of patients with autism." (PMID 38698428, 2024). "Furthermore, interactions between PNNs and parvalbumin interneurons are altered in mouse models of autism." (PMID 35721494, 2022).
autism (continued). "A previous study of adult males with autism also showed a decrease in calretinin-positive interneurons specifically localized in the dentate gyrus of the hippocampus and more widespread changes in parvalbumin-positive interneuron numbers." (PMID 31417418, 2019). "Moreover, dysfunction in parvalbumin cells has been observed in various mouse models of autism." (PMID 38698428, 2024). "In murine models of autism by prenatal exposure to valproic acid or genetic modification, deficits in PPI as well as decreases in parvalbumin-positive neurons in the SC were reported." (PMID 28261046, 2017). "The number of parvalbumin-expressing inhibitory interneurons, as well as GABA receptors and the receptors’ benzodiazepine binding sites, is reduced in autism, suggesting reduced cortical inhibition." (PMID 25400705, 2014). "Both parvalbumin-immunoreactive neuronal density and calbindin-immunoreactive neuronal density were preserved in the PCC in the autism cases relative to matched controls." (PMID 24278731, 2012). "We provide morphological evidence, that in idiopathic and dup-15 autism, accumulation of N-tr-Aβ with and without pyroglutamate-11 modified N-terminus affects mainly the parvalbumin-expressing subpopulation of GABAergic neurons." (PMID 32345355, 2020). "In this study, we provide morphological evidence that abnormal accumulation of N-tr-Aβ with and without pyroglutamate-11 modified N-terminus in autism affects mainly the subpopulation of GABAergic neurons expressing parvalbumin, but not those expressing somatostatin." (PMID 32345355, 2020).
cognitive deficits (40 papers, 2012 to 2025). "First, although NO ameliorated cognitive impairment in the VD mouse model by reducing the loss of parvalbumin neurons, the specific underlying regulatory mechanism requires further exploration." (PMID 40337954, 2025). "Sevoflurane exposure resulted in cognitive impairment that was associated with decreased synCAM1 expression in parvalbumin (PV) interneurons, a reduction of PV phenotype, disturbed gamma oscillations, and dendritic spine loss in the hippocampal CA3 region." (PMID 38105652, 2023). "In that study, male mice were more susceptible than female mice to pain-related cognitive deficits associated with morphologic changes in the parvalbumin interneuron and pyramidal neuron in the infralimbic cortex in males." (PMID 31901234, 2020). "The dysfunction or phenotypic loss of parvalbumin (PV)-positive neurons has been implicated in cognitive deficits." (PMID 32218736, 2020). "Furthermore, we found that the NO metabolite improved cognitive impairment by reducing the loss of parvalbumin-positive neurons." (PMID 40337954, 2025). "More importantly, a NOBM can reduce the loss of parvalbumin neurons; this may be why NO metabolites in the herbal mixture result in improved cognitive impairment in VD mice." (PMID 40337954, 2025). "Here we demonstrated that dietary intake of glucoraphanin (GF), the precursor of a natural antioxidant sulforaphane, during juvenile and adolescent stages prevented cognitive deficits and loss of parvalbumin (PV) immunoreactivity in the medial prefrontal cortex (mPFC) of adult offspring after MIA." (PMID 29391571, 2018). "Changes in interneuron numbers have been widely implicated in a number of cognitive deficits, therefore we quantified cortical interneuron populations including parvalbumin (PV+), calretinin (CR+), and neuropeptide Y (NPY+) interneurons in EfnB1Y/+ and EfnB1Y/− mutants." (PMID 24520368, 2014). "Application of optogenetic and pharmacogenetic techniques to activate parvalbumin neurons in the mPFC successfully reversed the cognitive impairments observed in the anti-NMDAR-IgG-treated mice." (PMID 40071389, 2025). "They show that injecting anti-NMDAR antibodies into the medial prefrontal cortex of mice leads to cognitive impairments and dysfunction of parvalbumin-positive interneurons, mirroring changes observed in humans." (PMID 40071389, 2025). "Disruption of NRG1-ErbB4 signaling in the parvalbumin-positive interneurons partially contribute to the isoflurane-induced hippocampus-dependent cognitive impairment in aged mice exposed to isoflurane, which can be reversed by exogenous NRG1-β1." (PMID 39959423, 2025). "It restored the glutamatergic neurotransmission and activated the parvalbumin-positive GABAergic interneurons ameliorating the cognitive deficits and the histopathological alterations in the prefrontal cortex." (PMID 40711497, 2025). "For instance, restoring the intrinsic excitability of parvalbumin-expressing interneurons, increased γ-oscillations, and reversed cognitive impairment in the human APP AD model." (PMID 37163441, 2023). "Additionally, the expression of calbindin-rich matrix cells and parvalbumin-rich core cells was examined to assess how the connectivity property of thalamic cells, and its disruption, can relate to cognitive deficits following a thalamic stroke." (PMID 41245369, 2025). "Although previous literature shows that cognitive impairment and localised parvalbumin deficits do occur in single-hit isolation-reared female rats, emerging findings demonstrate that microglial activation is much more pronounced in isolation-reared male than female mice." (PMID 38363536, 2024). "Furthermore, a hallmark of the pathophysiology of this disease is the dysfunction of cortical inhibitory γ-aminobutyric acid (GABA) neurons expressing parvalbumin (PV), which is also involved in cognitive impairment." (PMID 26107664, 2015).
cognitive deficits (continued). "Interestingly, dietary intake of SFN’s precursor, GRA, during childhood and adolescence prevented the onset of cognitive deficits, the increase in 8-oxo-dG-positive cells, and the reduction in parvalbumin-positive cells in the brain (mPFC and CA1) induced by phencyclidine in adult mice." (PMID 40722922, 2025). "Indeed, recently, the overexpression of MHC-I in astrocytes has been shown to activate microglial cells, to decrease the number of parvalbumin-positive neurons and to reduce dendritic spine density in the mouse prefrontal cortex, leading to social and cognitive deficits." (PMID 33920048, 2021). "First, we performed behavioral tests (locomotion and NORT) and parvalbumin (PV) immunohistochemistry in juvenile offspring after MIA because the reduction of PV immunoreactivity in the medial prefrontal cortex (mPFC) might be related with cognitive impairment and psychosis." (PMID 29391571, 2018). "Additionally, orexin also directly affects neurons that are important for executive functions, e.g., parvalbumin-positive interneurons in the PFC, and could thereby rescue cognitive deficits." (PMID 39478089, 2025).
Alzheimer disease (33 papers, 2013 to 2026). A progressive, neurodegenerative disease characterized by loss of function and death of nerve cells in several areas of the brain leading to loss of cognitive function such as memory and language. "Consistently, animal models for Alzheimer’s disease as well as aging showed a significant drop of parvalbumin GABAergic neurons in the hippocampus, which was associated with a lower gamma power." (PMID 31805729, 2019). "Other observations also support the model in which parvalbumin interneurons being less active causes defects in neural circuits in Alzheimer’s disease." (PMID 28440224, 2017). "Selective accumulation of alpha-synuclein in microglia leads to progressive degeneration of dopaminergic neurons, and microglia-mediated plaque-driven loss of perineuronal nets and subsequent reduction of parvalbumin-positive interneurons in Alzheimer’s disease mouse model." (PMID 36262885, 2022). "The gene PVALB encodes a high affinity calcium ion-binding protein that is structurally and functionally similar to calmodulin and troponin C. Calcium binding proteins like Calmodulin have been previously reported to be involved in Amyloid plaques formation and are linked to Alzheimer’s disease." (PMID 33282526, 2020). "The present study demonstrates the effects of an every-other-day (EOD) feeding regimen on parvalbumin (PV)-expressing interneurons in the cortex of 5xFAD mice, a well-established animal model of Alzheimer’s disease (AD)." (PMID 41313510, 2025). "In the mouse model of Alzheimer’s disease, we found that synaptic degeneration of parvalbumin neurons occurred in memory-related regions, which are inconsistent with amyloid-β plaque distribution." (PMID 36161898, 2022). "Parvalbumin expression is also reduced in neurodegenerative diseases, such as Alzheimer’s disease and Parkinson’s disease." (PMID 33632310, 2021). "As a possible mechanism, the lower expression of the voltage-gated sodium channel subunit Nav1.1 in the parvalbumin-GABAergic neurons was reported in the hAPPJ20 mouse as well as in Alzheimer’s disease patients." (PMID 31805729, 2019). "Here the authors show that optogenetic stimulation of medial septum parvalbumin neurons at 40 Hz rescues memory retrieval in the J20 mouse model of Alzheimer’s disease." (PMID 31757962, 2019). "Using novel quantitative analyses of spontaneous synaptic currents in L2/3 pyramidal cells, we revealed subtle deficits in the function of parvalbumin-expressing interneurons (PV INs) in a new mouse model of Alzheimer’s disease (AD), the AppNL-F mice." (PMID 30105300, 2018). "The ability to detect reduced NPTX2 in cerebrospinal fluid is relevant because targeting parvalbumin interneurons in particular, and circuit defects in general, is emerging as a potential way to treat cognitive impairments in patients with Alzheimer’s disease." (PMID 28440224, 2017). "In Alzheimer’s disease, somatostatin expression is decreased by 50% in the AONca and co-localizes with amyloid β, whereas parvalbumin and somatostatin levels are up- and downregulated, respectively, in the piriform cortex." (PMID 29259548, 2017). "For example, patients with Alzheimer’s disease and mouse models of the disease also have reduced levels of a sodium channel called Nav1.1, which is critical for parvalbumin interneuron activity." (PMID 28440224, 2017). "A recent study shows that enhancing parvalbumin interneuron activity in a mouse model of Alzheimer’s disease can decrease the accumulation of amyloid peptides in the brain." (PMID 28440224, 2017). "Beyond SCZ, dysregulation of PVALB-, SST-, and VIP-expressing interneurons has been implicated in a range of neuropsychiatric and neurodegenerative conditions including bipolar disorder, major depression, autism spectrum disorder, and Alzheimer’s disease." (PMID 41159096, 2026).
Alzheimer disease (continued). "Thus, the high metabolic load of parvalbumin-expressing interneurons makes them potentially vulnerable to failures in the vascular network due to aging, Alzheimer’s disease as well as stroke." (PMID 40497449, 2025). "When NPTX2 is overexpressed in neurons in the Tau P301S model of frontotemporal dementia (FTD) and Alzheimer’s Disease (AD), the level of the complement C4b and synapse engulfment decreases, leading to increased number of excitatory synapses on parvalbumin interneurons." (PMID 39258226, 2024). "Dysfunction in fast-spiking parvalbumin interneurons (PV-INs) may represent an early pathophysiological perturbation in Alzheimer’s Disease (AD)." (PMID 38561349, 2024). "Recent studies have implicated impaired Parvalbumin Fast-Spiking Interneuron (PVIN) function as a precipitating factor underlying abnormalities in network synchrony, oscillatory rhythms, and cognition associated with Alzheimer’s disease (AD)." (PMID 35645763, 2022). "Ablation of NRG3 and ERBB4 leads to a reduction in the number of excitatory synapses on small parvalbumin-positive interneurons, altered short-term neuroplasticity, and disinhibition of the hippocampal network, which plays a critical role in intercellular communication in alzheimer’s disease." (PMID 38383423, 2024). "Gamma induction may be neuroprotective against neurodegenerative diseases and animal models of Alzheimer's disease have allowed to demonstrate that repetitive sensory gamma entrainment improves the function of fast-spiking parvalbumin-positive interneurons as well as microglia." (PMID 35390460, 2022). "For example, PVALB, specifically expressed in the posterior hippocampus, was also highly expressed in brain regions functionally connected and structurally covarying with the posterior hippocampus, as well as in regions specifically vulnerable to Alzheimer’s disease." (PMID 32075960, 2020). "For example, modulation of hippocampal theta activity by somatostatin positive, but not parvalbumin positive, GABAergic neurons in a mouse model of Alzheimer’s disease has been demonstrated." (PMID 34966904, 2021).
depression (24 papers, 2014 to 2026). "Early adversity, the loss of the inhibitory GABAergic interneuron parvalbumin, and elevated neuroinflammation are associated with depression." (PMID 38672480, 2024). "Depression is linked to changes in GABAergic inhibitory neurons, especially parvalbumin (PV) interneurons, which are susceptible to redox dysregulation." (PMID 38139008, 2023). "Other studies have reported that chronic exposure to stress enhanced parvalbumin-expressing GABAergic interneurones underlies depression-like behaviour." (PMID 33114753, 2020). "In the VP, glutamatergic and GABAergic neurons play distinct roles in aversion processing and reward reinforcement learning, respectively; parvalbumin-positive neurons modulate depression-like behaviours." (PMID 37069246, 2023). "Dysfunction of parvalbumin (PV) neurons is closely involved in depression, however, the detailed mechanism remains unclear." (PMID 38044302, 2024). "Parvalbumin (PV) increases in several depression mice models." (PMID 38044302, 2024). "Constitutive AHNAK knockout mice and forebrain glutamatergic neuron-selective AHNAK knockout mice were found to have a depression-like behavioral phenotype, whereas parvalbumin interneuron-selective AHNAK knockout mice displayed an antidepressant-like behavioral phenotype." (PMID 33971621, 2021). "Moreover, the decrease in PVALB methylation at CpG4 correlated strongly with severity of depression." (PMID 31588185, 2019). "In Subgroup 4, endogenous, neurotic, and syndromic form of depression, similar to mental depression observed in Subgroup 1, were enriched in SST interneurons, whereas those with bipolar disorder were enriched in Parvalbumin (PV)-positive and CRH-positive interneurons." (PMID 33504954, 2021). "Here, we provide further evidence supporting the role of cortical GABAergic interneurons, mainly somatostatin- and parvalbumin-expressing cells, required for the optimal E:I balance in the PFC and discuss how the malfunction of these cells can result in depression-related behaviors." (PMID 30914923, 2019).